C10orf95 (chromosome 10 open reading frame 95)
Synonyms: FLJ14280
Gene: Protein-coding gene on chromosome 10 (102,449,837 to 102,451,543, reverse strand). Ensembl gene ENSG00000120055.
Genetic constraint (gnomAD): Missense variants: 78 observed, 35.8 expected, observed/expected ratio (o/e) 2.18. Synonymous variants: 34 observed, 17.66 expected, observed/expected ratio (o/e) 1.93, 90% interval 1.39 to 1.98.
Homologues: Orthologues: chimpanzee C10H10orf95 (99% identical), dog C10orf95 (65% identical), rat C1h10orf95 (55% identical), mouse 2310034G01Rik (54% identical).
Diseases named in the same sentence as C10orf95 in open-access papers:
C10orf95 is named in the same sentence as 1 disease in open-access papers, as found by Europe PMC text mining. Sharing a sentence is not in itself a finding about the gene and the disease.
C10orf95 shares sentences with these, for which no sentence is quoted: gastric cancer (1 paper).